PRL (prolactin)
Diseases named in the same sentence as PRL in open-access papers (continued):
Sharing a sentence is not in itself a finding about the gene and the disease.
hypogonadism (continued). "In contrast, as body weight was stable at follow-up, changes in lipid parameters seem to be independent of body composition and might, in addition to hypogonadism, rather be a direct consequence of prolactin normalization or dopamine agonist-induced D2R activation, as previously suggested." (PMID 33902531, 2021). "Thus, increased concentration of estradiol and prolactin may also be liable for the origin of hypogonadism in the present study." (PMID 23766852, 2013). "Overall, the rise of prolactin affects negatively the secretion of FSH and LH, eventually leading to hypogonadism." (PMID 40406467, 2025). "Interestingly, one study found that men with SZ on prolactin-raising antipsychotics had higher rates of osteoporosis and low bone mineral density than women, which might reflect that clinicians are less likely to intervene for hypogonadism in men." (PMID 40589655, 2025). "Serum testosterone significantly correlated with gonadotropins levels, prolactin, SHBG, and FTI scores in patients with hypogonadism before surgery." (PMID 39337013, 2024). "In the absence of acute/subacute illness, blood testosterone, follicular stimulating hormone FSH) and luteinizing hormone (LH) levels, as well as serum prolactin (PRL) levels, should be measured in males with suspected hypogonadism." (PMID 36875199, 2023). "Attention should also be given to hypogonadism in female patients, the HPT and somatotropic axes, and prolactin secretion in both sexes, as we currently lack data on these areas." (PMID 31511863, 2020). "Of note, persistent hypogonadism after PRL normalization showed a negative correlation with RBC, HCT, and Hb levels, whereas hypothyroidism and any hormonal replacement therapy had no significant impact on hematological parameters." (PMID 39900728, 2025). "Patients with compression of gonadotropic lineage within the pituitary are supposed to less or not recover from hypogonadism despite the normalization of prolactin." (PMID 39109291, 2024). "A CT pituitary scan was arranged for hypogonadism for six patients who did not have a raised prolactin." (PMID 38098129, 2023). "Cabergoline was able to improve metabolic parameters even without the correction of PRL excess or concomitant hypogonadism." (PMID 36704037, 2022). "Especially, case 3 was overweight, showed hypogonadism, and had high fasting insulin which could be attributed to the patient’s elevated levels of serum GH, IGF-1, and PRL." (PMID 35002961, 2021). "In men with suspected hypogonadism LH, FSH, testosterone and PRL levels should be dosed." (PMID 33790864, 2021). "Since hypogonadism did not recover after PRL reduction, 3 attempts of testosterone substitutive treatment were done, observing a rise in PRL levels." (PMID 34173929, 2021). "In males with suspected hypogonadism, it is recommended to measure the serum testosterone, FSH, and LH in the absence of acute/subacute illness and before 10 am (after an overnight fast) combined with a serum prolactin (PRL) level." (PMID 31065469, 2019). "It is interesting that case 3 never developed hypogonadism and even had a normal puberty, although always maintaining very high concentrations of prolactin." (PMID 30542321, 2018). "Other rarer hormonal findings may be hypothyroidism and hypoadrenalism, hypogonadism, or overproduction of adrenocorticotropic hormone (ACTH), growth hormone (GH), or prolactin." (PMID 22312541, 2012). "However, 5 men (10.6%) did not achieve prolactin normalization, of whom 3 men (60.0%) remained with hypogonadism at the end of follow-up." (PMID 40199840, 2025). "Eleven patients had a CT pituitary for hypogonadism and did not have a raised prolactin." (PMID 38098129, 2023). "However, although patients with hypogonadism have higher median levels of PRL, it was not possible to demonstrate weight differences according to gonadal function." (PMID 36704037, 2022).
hypogonadism (continued). "Although the regression analysis did not confirm an association between BMI and PRL parameters at baseline, literature supports increased BMI and/or body fat in patients with PRL, which correlates with baseline prolactin levels and may be independent of hypogonadism." (PMID 38645431, 2024).
diabetes (95 papers, 2008 to 2026). "Some studies have used western blotting to explore prolactin in the brain, although these focused on its potential involvement in Alzheimer’s disease associated with diabetes." (PMID 40806430, 2025). "Findings from phase-1 of the association between low PRL and increased rates of diabetes are therefore consistent with reports from previous cross-sectional studies." (PMID 38829475, 2024). "Of note, lower serum PRL during pregnancy has been associated with a higher risk of postpartum prediabetes/diabetes." (PMID 39172174, 2024). "The weaker association of PRL < 5 ng/ml (106 mIU/l) with the presence of diabetes strengthens this evidence and merits further study." (PMID 38829475, 2024). "As a matter of fact, PRL levels ranging 25–40 ng/ml have been found associated with a lower prevalence of type 2 diabetes mellitus, metabolic syndrome, NAFLD, and major cardiovascular events." (PMID 39078526, 2024). "Our findings are in contrast to those observed in previous studies where higher PRL levels were found to associate with greater risk of incident diabetes, and treatment to reduce PRL levels with a dopamine agonist (Bromocriptine) improves glycaemic control." (PMID 38829475, 2024). "The association between serum prolactin level and IR are also seen in the patients with obese and diabetes." (PMID 36823522, 2023). "13.8% weight gain.2.10% risk of diabetes.00.24% deterioration lipid profile.34% prevalence of metabolic side effects.Withdrawal dyskinesias, increased prolactin levels, weight gain, and other metabolic abnormalities." (PMID 37623307, 2023). "In the normoprolactinemic population in general, higher PRL levels within the normal range were associated with improved insulin sensitivity and glucose metabolism, and lower prevalence of diabetes and metabolic syndrome." (PMID 36704037, 2022). "First, circulating levels of the pituitary hormone, prolactin, increase during pregnancy and lactation, and a recent study confirmed that prolactin levels are inversely associated with the risk of type 2 diabetes mellitus, even with 22 years of follow-up." (PMID 35045125, 2022). "Data is inconsistent and, for the most part, not sufficient to demonstrate the association between serum Prolactin (PRL) concentration within the physiologic range and the incidence rate of type 2 Diabetes Mellitus (DM) among men." (PMID 36471299, 2022). "Low PRL levels were associated with higher risk of MS, polycystic ovary syndrome, postpartum diabetes and diabetes mellitus type 2 in population studies." (PMID 36704037, 2022). "Conversely, higher circulating PRL levels were associated with lower prevalence of diabetes and impaired glucose regulation in a large cohort of middle-aged and elderly men and postmenopausal women." (PMID 29867762, 2018). "Vasoinhibins are prolactin fragments present in the retina, where they have been shown to prevent the hypervasopermeability associated with diabetes." (PMID 25368550, 2014). "Surely, accompanying metformin therapy for diabetes mellitus and life style changes had additive effects concerning the wonderful weight loss, but cabergoline contribution by prolactin reduction cannot be denied." (PMID 23762662, 2013). "Both high and low prolactin levels are associated with the risk of diabetes." (PMID 40650124, 2025). "The use of relatively higher PRL cut-offs may suffer from a dilution effect since individuals with lower risk for diabetes are included in the lowest PRL category." (PMID 38760578, 2024). "A moderate increase in prolactin is associated with a decreased incidence of diabetes mellitus." (PMID 39425884, 2024). "Low prolactin levels in men predispose them to mood disturbances, sexual dysfunction, and diabetes." (PMID 39456268, 2024).
diabetes (continued). "Our findings also suggest that 25-hydroxyvitamin D levels should be measured routinely in hyperprolactinemic women at high risk for cardiovascular disease or diabetes, but ideally in all women with prolactin excess who require treatment with a dopamine agonist." (PMID 37242186, 2023). "However, in other studies, PRL levels were inversely correlated to the risk of diabetes and dyslipidemia." (PMID 36704037, 2022). "Interestingly enough, low levels of PRL in population studies were associated with diabetes mellitus type 2 risk and metabolic syndrome." (PMID 36704037, 2022). "Consistently, high serum PRL in pregnancy predicts a lower risk of postpartum prediabetes/diabetes, and in women with gestational diabetes mellitus, lower PRL levels at 6 to 9 weeks postpartum associate with a higher future risk of developing T2D in a 10-year follow up." (PMID 36213259, 2022). "Regarding β-cell function, pregnant women with high PRL levels have a lower postpartum risk of developing diabetes and β-cell dysfunction, and women with polycystic ovary syndrome (PCOS) with PRL levels in the 4th quartile show lower prevalence of β-cell dysfunction." (PMID 36213259, 2022). "Low serum PRL may indicate a higher risk of developing metabolic syndrome and type 2 diabetes mellitus." (PMID 32477263, 2020). "Because β-cell replication in neonates plays a major role in β-cell mass in adult humans, the regulation of β-cell mass by prolactin signaling in postnatal pancreas may be implicated in an individual's susceptibility to diabetes." (PMID 25126749, 2014). "In men, it is possible that only a very low PRL level could increase the risk of future diabetes." (PMID 38760578, 2024). "Non-thyroid laboratory surveillance before treatment was limited, with only two patients checked for adrenal function, three for reproductive hormones, four for growth-related analytes, one for hypophysitis/abnormal prolactin, and one for diabetes." (PMID 39680426, 2025). "There was also an increasing trend in prediabetes and diabetes based on fasting blood glucose levels was observed with lower categories of PRL." (PMID 38829475, 2024). "The obtained results indicate that metformin treatment should be considered in middle-aged elderly men with diabetes or prediabetes coexisting with an elevated prolactin concentration." (PMID 39204081, 2024). "An increasing trend in prediabetes and diabetes based on fasting blood glucose levels was observed with lower categories of PRL." (PMID 38829475, 2024). "We recognize that the effect of low PRL on diabetes, and indeed other metabolic disorders, is difficult to determine probably because the effects are thought to be minor." (PMID 38760578, 2024). "Antipsychotics confer risk of long-term serious side effects, including irreversible movement disorders, weight gain, hyperlipidemia, metabolic syndrome, diabetes, and elevated prolactin levels." (PMID 39103898, 2024). "Both groups were similar in age, sex, body mass index, diabetes duration, HbA1c, serum creatinine, glomerular filtration rate, and serum PRL levels at baseline." (PMID 37673971, 2024). "Of the studies examining maternal PRL in pregnancies affected by maternal diabetes, only two attempted to relate PRL to fetal, birth, or infant outcomes." (PMID 36769162, 2023). "In concordance with epidemiologic studies, circulating levels of PRL are reduced in the ob/ob and db/db obese and diabetes mouse models, and in streptozocin-induced (STZ) T2DM rats." (PMID 36993818, 2023). "For instance, children and adolescents under psychotropic medications face a greater likelihood of developing side effects like withdrawal kinesis, increased prolactin levels, weight gain, and other metabolic abnormalities, including type 2 diabetes mellitus." (PMID 37623307, 2023). "Influencing factors of prolactin levels in patients with diabetes mellitus: multiple linear regression model." (PMID 36329924, 2022).
diabetes (continued). "As a result, serum PRL concentrations within the physiologic range might reduce the risk of developing type 2 Diabetes Mellitus (DM)." (PMID 36471299, 2022). "The PRL levels in the patients with diabetes were above the conventional threshold of 25 ng/ml, and therefore in the homeoFIT-range." (PMID 36157442, 2022). "Regarding diabetes and its complications, there is a new trend towards the recognition of PRL as an important metabolic hormone, directly involved in beta-cell function and survival, and the regulation of insulin sensitivity and resistance, respectively." (PMID 36157442, 2022). "As a result, we set out to look into the relationship between serum PRL and the risk of MAFLD in patients with type 2 diabetes mellitus (T2DM)." (PMID 35222274, 2022). "PRL treatment reduces blood glucose levels in STZ-induced diabetes in mice but high doses of the hormone induce β-cell apoptosis in 90% pancreatectomized rats." (PMID 33746901, 2021). "Two preclinical studies have addressed the effect of PRL administration on diabetes outside pregnancy." (PMID 33746901, 2021). "We conclude that PRL protects whole body glucose homeostasis by reducing β-cell loss and pancreatic inflammation in STZ-induced diabetes." (PMID 33746901, 2021). "In order to determine independent risk factors, age, BMI, smoking, hypertension, diabetes, testosterone, estradiol, TSH, and prolactin were considered as confounders in the regression models." (PMID 32728148, 2020). "Prolactin (PRL) secretion is also determined by sex, age, and BMI, and high circulating PRL is associated with lower prevalence of diabetes and hypolipidemia." (PMID 33075214, 2020). "Anova Comparisons of birth weight, maternal prolactin and cord blood prolactin between uncomplicated pregnancies, Gestational hypertension, Gestational diabetes and preterm labour groups." (PMID 31372154, 2019). "While, TSH and PRL levels appear to be lower in patients with premature ejaculation and diabetes mellitus than in controls." (PMID 29556396, 2018). "Therefore, although the effect on prolactin levels was relatively mild and limited to patients with elevated prolactin levels, metformin may be useful in hyperprolactinaemic patients at high risk of diabetes and cardiovascular disease." (PMID 25239203, 2015). "It has been noted that higher prolactin levels in older individuals without diabetes are associated with improved insulin sensitivity and lower glycemic values." (PMID 40650124, 2025). "Thyroid surveillance continued among all 18 patients after ICI initiation (100 %), while non-thyroid surveillance continued to be limited seven patients were checked for adrenal function, six for reproductive hormones, six growth related analytes, three for prolactin, and four for diabetes mellitus." (PMID 39680426, 2025). "The underlying mechanisms linking hypoprolactinemia and development of type 2 diabetes are unclear, but the association of PRL with diabetes is independent of age, adiposity, smoking, and alcohol consumption." (PMID 38829475, 2024). "This might be due to polycystic ovary syndrome, thyroid diseases, diabetes mellitus, prolactin abnormalities and implantation failure seen commonly in women with endocrine disease." (PMID 36895657, 2023). "Overall, prolactin levels appeared to be lower in pregnancies affected by type 1 diabetes mellitus." (PMID 36769162, 2023). "Eligible studies included women who were pregnant or up to 12 months postpartum and had a pre-existing diagnosis of type 1 or type 2 diabetes mellitus or polycystic ovary syndrome; with reporting of at least one endogenous maternal serum prolactin level during this time." (PMID 36769162, 2023). "This may be another reasonable explanation for the lower PRL level in the clinical subgroup of diabetes." (PMID 36329924, 2022). "Finally, because of exclusion criteria, the impact of subnormal prolactin levels on statin action in individuals with cardiovascular disease or diabetes requires further research." (PMID 36195057, 2022).
diabetes (continued). "In addition, the signaling pathways of prolactin, Rap1, Ras, and FoxO are involved in insulin production or the pathology of diabetes." (PMID 36159557, 2022). "Furthermore, there are few studies where researchers demonstrated the connection between PRL and diabetes." (PMID 36329924, 2022). "This study aimed to investigate whether PRL is related to bone mineral density (BMD) in type 2 diabetes mellitus (T2DM)." (PMID 36313749, 2022). "The PRL/vasoinhibin axis and its regulation in diabetes is among the factors beyond glycemic exposure which may determine the risk of DME, and DR." (PMID 36157442, 2022). "Therapeutic interventions are currently evaluated in a clinical trial and will show whether patients with diabetes benefit from raising circulating PRL levels." (PMID 36157442, 2022). "Based on these observations and those of our current findings, we conclude that drugs elevating PRL levels within the HomeoFIT-PRL range may prove to be a promising therapy for diabetes." (PMID 33746901, 2021). "To investigate the protective effect of endogenous PRL against diabetes outside pregnancy, we compared the number of cases and severity of streptozotocin (STZ)-induced hyperglycemia between C57BL/6 mice null for the PRL receptor gene (Prlr-/-) and wild-type mice (Prlr+/+)." (PMID 33746901, 2021). "Because, STZ elicits the apoptosis of β-cells through the generation of cytotoxic free radicals and the promotion of pancreatic inflammatory responses, our findings suggest that PRL counteracts diabetes by blocking oxidative stress and pancreatic inflammation early after STZ treatment." (PMID 33746901, 2021). "Yet it is unclear whether the action of endogenous PRL on glucose homeostasis protects against diabetes outside pregnancy." (PMID 33746901, 2021). "The expression and effect of the PRLR on alpha cells have not been described and further research is needed to elucidate whether α−cells are direct targets of PRL in diabetes." (PMID 33746901, 2021). "In contrast, higher prolactin levels within the normal range have been linked to lower risks of diabetes in middle-aged, non-pregnant populations." (PMID 32180760, 2020). "Historically, there are several reports in which a rise in systemic PRL levels, and a subsequent rise in retinal vasoinhibins, may have contributed to the improvement of retinal vascular alterations in patients with diabetes." (PMID 29896154, 2018). "Prolactin (PRL) is known to directly increase β-islet cell insulin secretion and PRL level has been recently linked to deficient glucose regulation and the state of diabetes itself." (PMID 29975740, 2018). "Moreover, diabetes damages all retinal cell types and PRL, itself, ameliorates neuronal, glial, and pigment epithelium dysfunction in the retina." (PMID 29896154, 2018). "Also, it is known that prolactin has direct effects on increasing insulin secretion and is closely related to diabetes." (PMID 28361687, 2017). "On the other hand, experimental studies also showed that PRL has effects on growth of pancreatic ß-cells and reduces threshold for glucose-stimulated insulin secretion, which indicate that PRL has a protective effect against type 2 diabetes mellitus." (PMID 28384295, 2017). "Furthermore, bromocriptine, a dopamine agonist that is well known to suppress serum PRL levels, has been shown to effectively improve insulin sensitivity, and has been approved for the treatment for type 2 diabetes mellitus in the United Sates." (PMID 28384295, 2017). "Raising circulating PRL levels leads to vasoinhibin accumulation in the retina, and the elevation of intraocular vasoinhibins prevents and reverses diabetes-induced excessive retinal vasopermeability in rats and angiogenesis in a mouse model of retinopathy of prematurity." (PMID 29163363, 2017). "Vasoinhibins are N-terminal fragments of prolactin that prevent BRB breakdown during diabetes." (PMID 29026201, 2017).